MMACHC (metabolism of cobalamin associated C)
Diseases named in the same sentence as MMACHC in open-access papers (continued):
Sharing a sentence is not in itself a finding about the gene and the disease.
organic acidemias (1 paper, 2022). "Among organic acidemias, cobalamin metabolism disorders were the most common (5%), caused by frameshift mutations in MMACHC gene, in the majority of cases." (PMID 36468010, 2022).
vitamin deficiency (1 paper, 2020). A disorder that is caused by the deficiency of a vitamin. "Cobalamin disorder is an inborn vitamin deficiency characterized by neurodevelopmental abnormalities, most often owing to biallelic mutations in the MMACHC gene, whose gene product MMACHC is a key enzyme in the cobalamin (vitamin B12) metabolic pathway." (PMID 31905202, 2020).
von Hippel-Lindau disease (1 paper, 2022). An autosomal dominant disorder caused by pathogenic variants in the VHL gene, leading to an increased risk of various benign and malignant tumors, including hemangioblastomas, retinal hemangiomas, endolymphatic sac tumors, renal cell carcinoma, and pheochromocytomas.
metabolic disease (6 papers, 2017 to 2024). A congenital disorder (due to inherited enzyme abnormality) or acquired (due to failure of a metabolically important organ) disorder resulting from an abnormal metabolic process. "The new strategy identified the opportunity to reclassify these variants in MMUT and MMACHC in the current database and may enable us to prioritize and target the pathogenicity of variants in other inherited metabolic diseases for evaluation." (PMID 39076170, 2024). "The majority of the literature focuses primarily on the function of HCFC1 at the MMACHC promoter in the human syndrome, cblX. cblX disorder is the result of mutations in the HCFC1 gene and these mutations disrupt protein function causing a decrease the expression of MMACHC and a metabolic disorder." (PMID 32522152, 2020). "A few cases of non-mitochondria-related variants were evaluated as probably having mitochondrial disorders, such as variants in MMACHC, MCEE, FOLR1 and G6PC genes, which were grouped as causative genes of metabolic diseases affecting multiple systems." (PMID 36918699, 2023). "No sequence variant in MMACHC was identified in the father and no additional gene mutations were identified in the patient and her relatives using the TruSight NGS Illumina panel of the genes involved in metabolic diseases." (PMID 29302025, 2018).
genetic disorders (2 papers, 2021 to 2022). "In terms of treatability, TSC1-, TSC2-, SLC35A2-, ATP7A-, ALDH7A1-, and MMACHC-related disorders had specific therapeutic regimens and accounted for 18.5% (19/103) of the cases with genetic disorders." (PMID 35330882, 2022).
renal disease (1 paper, 2022). "Therefore, we speculated that Chinese dominant cblC-associated renal disease might be highly associated with MMACHC pathogenic variant c.80A > G." (PMID 36704130, 2022).
MMACHC also shares sentences with these, for which no sentence is quoted: phenylketonuria (4 papers); carnitine deficiency (2); megaloblastic anemia (2); 2-methylbutyryl-CoA dehydrogenase deficiency (1); Alpha-thalassemia (1); Alzheimer disease (1); cancer (1); cardiovascular diseases (1); cerebral palsy (1); chronic renal insufficiency (1); congenital adrenal hyperplasia (1); COPA syndrome (1); epilepsy (1); Familial exudative vitreoretinopathy (1); glutaric aciduria (1); Hyperphenylalaninemia (1); Hypertension (1); Intellectual disability (1); intellectual impairment (1); maple syrup urine disease (1); Pigmentary retinopathy (1); retinal degeneration (1); short chain acyl-CoA dehydrogenase deficiency (1); spinal muscular atrophy (1); Wilson disease (1).